BECN1 (beclin 1)
Diseases named in the same sentence as BECN1 in open-access papers (continued):
Sharing a sentence is not in itself a finding about the gene and the disease.
tumor (continued). "A link between autophagy and cancer has been appreciated through the observation that Beclin 1, a phylogenically conserved protein essential for autophagy, is a haplo-insufficient tumor suppressor." (PMID 20454448, 2010). "A dose- and time-dependent induction of autophagy observed in tumor cells following cisplatin treatment is evidenced by up-regulation Beclin-1 and cisplatin-triggered activation of AMPK pathway leading to a subsequent suppression of mTOR activity." (PMID 21191146, 2010). "Other bona fide autophagy genes including Beclin 1 have been shown to act as tumor suppressor genes in cancer." (PMID 20184741, 2010). "The tumor development in Beclin 1+/− mice indicates the importance of a full level of Beclin 1 expression for its tumor suppressor function." (PMID 20454448, 2010). "Beclin 1, the mammalian orthologue of the yeast Atg6/Vps30 gene, is the first identified tumor suppressor gene in human to mediate autophagy." (PMID 20230646, 2010). "The mean ± SD beclin 1/β-actin mRNA level was 1.56 ± 1.01 for tumor tissues and 2.24 ± 1.39 for adjacent normal tissues." (PMID 20230646, 2010). "Collectively, these findings suggest that BCc1 may act as a dual-function nanomedicine, capable of modulating tumor-suppressive autophagy (via Beclin-1) while inhibiting pro-survival autophagy (via ATG-4B)." (PMID 41550506, 2026). "Notably, this selective inhibition occurs alongside the context-dependent upregulation of Beclin-1, suggesting that BCc1 can concurrently promote tumor-suppressive autophagy while inhibiting pro-survival autophagic flux." (PMID 41550506, 2026). "Given the critical role of autophagic regulation in controlling tumor immune evasion and cell death, the present study investigates the effects of BCc1 on key autophagy-associated genes ATG-4B, ATG-7, Beclin-1 and the mTOR signaling pathway using a BALB/c mouse model of BC." (PMID 41550506, 2026). "However, at the same time, why simple readouts of beclin-1 expression alone provide variable prognostic signals across studies and tumour subsets." (PMID 41511337, 2025). "Beclin‐1 is active in tumor suppression and in the development of the immune system." (PMID 40488268, 2025). "However, its role in cancer is complex - while Beclin 1-mediated autophagy can act as a tumor suppressor by preventing genomic instability, excessive autophagy can promote tumor survival by enhancing chemoresistance." (PMID 40843353, 2025). "Importantly, this transcriptional reprogramming occurs in HT-29 cells, a model of apoptosis resistance, highlighting Beclin 1 suppression as a potential strategy to sensitise tumours that are otherwise refractory to caspase-dependent death." (PMID 40971030, 2025). "Several reports have indicated that BECN1 regulation of autophagy plays a role in tumor formation." (PMID 40754831, 2025). "Becn1 is a mammalian homolog of yeast Atg6 and an autophagy-related tumour suppressor gene." (PMID 40395993, 2025). "Beclin-1, a key autophagy-related protein, also functions as a tumor suppressor in mammalian cells." (PMID 40006067, 2025). "Additionally, administration of the autophagy inhibitor 3-methyladenine (3-MA) led to increased MTOR expression and downregulation of ATG5, ATG7, and BECN1, resulting in reduced tumor volume and elevated apoptosis cell death." (PMID 41502518, 2025). "Cell viability was assessed after 3-MA treatment and BECN1 knockdown using the CCK-8 assay to determine whether CANX-induced autophagy protects tumor cells." (PMID 39990231, 2025). "Since signalling pathways such as Akt and ERK directly modify Bcl-2 and beclin-1, the resulting phospho-patterns may predict the tumour’s responsiveness to upstream kinase inhibitors." (PMID 41511337, 2025). "Besides, autophagy promotes the regulation of tumor suppression by Beclin-1 through its interaction with UVRAG and Bax interaction factor-1 (Bif-1)." (PMID 40688079, 2025).
tumor (continued). "Among these, the expression levels of beclin-1 and Bcl-2 are particularly informative, as their relative abundance and the stoichiometry of their interaction can indicate whether a tumour is more likely to rely on autophagy or apoptosis during therapy." (PMID 41511337, 2025). "Autophagy also regulates tumor suppression through the interaction between Beclin-1 and Bcl-2." (PMID 40688079, 2025). "Notably, research has shown that mice with only a single functional copy of the autophagy-related gene Beclin-1 exhibit spontaneous tumor formation." (PMID 40001518, 2025). "Similarly, in the MG63 cell‐mediated xenograft model, a noticeable enhancement was observed in Beclin‐1 ubiquitination and degradation in the presence of shPRKDC along with anlotinib compared to tumours treated with control lentivirus and anlotinib." (PMID 39924638, 2025). "DAPK1 phosphorylates Beclin-1 to promote autophagy and inhibit tumor growth." (PMID 40868135, 2025). "Therefore, treating HER2-positive breast tumorgrafts with the Tat-BECN1 peptide inhibits tumor growth and promotes autophagy." (PMID 40754831, 2025). "This decline in Beclin 1 levels suggests that inhibition of autophagy may enhance tumor growth and proliferation." (PMID 38315272, 2024). "The BECLIN-1 protein is crucial in autophagy initiation and tumor suppression." (PMID 39555455, 2024). "Among mammalian ATG orthologs, Beclin-1 plays an important role in the formation of autophagosomes and the progression of autophagy; Beclin-1+/– mutant mice developed various tumors spontaneously, suggesting that it has a tumor suppression function." (PMID 38473345, 2024). "Furthermore, Beclin-1 has the potential to influence survival, prognosis, growth, and tumor recurrence." (PMID 39650649, 2024). "However, a hypoxic microenvironment and high expression of Beclin-1 increase autophagy and promote tumour cells’ survival." (PMID 39596186, 2024). "Beclin-1 is also involved in autophagosome formation and functions to inhibit tumor growth." (PMID 38948024, 2024). "Finally, we analyzed the possible function of Beclin-1 in tumor immunology and drug sensitivity in cancers." (PMID 39650649, 2024). "Furthermore, Beclin-1 plays a role in tumor spreading, blood vessel formation, and immune system regulation through its actions that are not related to autophagy." (PMID 39650649, 2024). "ATG12, BECN1 and MAP1LC3B (Microtubule-associated proteins 1A/1B light chain 3 B) were reported to be associated with the three autophagy-related lncRNA through analysis in Tumor Immune Estimation Resource (TIMER), Oncomine and Human Protein Atlas Database." (PMID 38291202, 2024). "Therefore, based on the function of Beclin-1, researchers are exploring drugs that target autophagy regulation to enhance the sensitivity of tumor cells to chemotherapy and targeted therapy." (PMID 39650649, 2024). "Additionally, Beclin-1 affects the antigen presentation capability of tumor cells, altering how tumor cells are recognized and attacked by the immune system, which allows tumor cells to partially evade immune surveillance." (PMID 39650649, 2024). "BECN1 T/N ratio was significantly negatively correlated with grade of tumor." (PMID 38787424, 2024). "Beclin 1, a mammalian homolog of yeast Atg6, is an autophagy-related tumor suppressor gene." (PMID 37856037, 2024). "When the level of autophagy induced by drug action on tumor cells is increased, the Beclin-1-Bcl-2 complex may be dissociated, thus producing autophagy-promoting and anti-apoptotic effects on tumor cells." (PMID 38932177, 2024). "On the other hand, therapy targeted at the BECN1 molecule can control tumor growth." (PMID 36830954, 2023). "On the other hand, the higher expression of BECN1 may be correlated with tumor hypoxia and may facilitate patient survival, suggesting that BECN1 may be a reliable marker for prognosing most patients with CRC." (PMID 37108476, 2023).
tumor (continued). "Beclin-1, which has a central role in autophagy, can function as a tumour suppressor (Ref." (PMID 36994671, 2023). "However, using autophagy inhibitors such as 3‐MA and HCQ to inhibit autophagy‐related genes like ATG5, ATG7 and Beclin 1 can re‐sensitize TAM‐resistant tumor cells." (PMID 37837401, 2023). "Notably, overall survival (p = 0.1525) was higher in patients bearing a tumor with high BECN1 expression (p = 7.372 × 10−6) than in those with low BECN1 expression." (PMID 37566004, 2023). "Furthermore, the phosphorylation levels of AMPK and BECN1 were increased in the tumor tissues of nude mice after APS treatment, as confirmed by Western blotting." (PMID 37733667, 2023). "It has also been shown that higher BECN1 expression is associated with longer survival of CRC patients, and, together with selected clinical parameters (T stage), may be an independent tumor prognostic factor." (PMID 36835075, 2023). "Results of a previous study demonstrated that the expression levels of Beclin‐1 in tumor cells were significantly reduced, and upregulation of these expression levels may play a role in tumor inhibition." (PMID 37051356, 2023). "In addition, BECN1 protein not only plays a key role as a regulator of autophagy but is also a tumor suppressor that shows reduced expression in several cancers." (PMID 37740192, 2023). "Additionally, the inhibition of autophagy by 3-methyladenine or by siRNA knockdown of BECLIN-1 diminished the anti-tumor activity of obatoclax in DLBCL cells." (PMID 37566004, 2023). "Beclin-1 was widely reported to have tumor-suppressive roles by several mechanisms, including autophagy of oncogenic proteins, activation of oncogene-induced senescence, anti-inflammatory responses, genetic stability, cell maintenance, and anti-microbial effects." (PMID 37736508, 2023). "The screening results suggested that the loss of two members of the E-cadherin complex, CDH1 and CTNNA1, could be mediators of the BECN1-mediated tumour suppressor mechanism." (PMID 37686639, 2023). "Beclin 1 is an essential mammalian autophagy gene and a haploinsufficient tumor suppressor." (PMID 37598181, 2023). "Thus, Beclin-1, as a breast-tumor-suppressor molecule, restricts tumor growth and metastases when E-cadherin is present at the cell surface." (PMID 37834467, 2023). "MAPK-activated protein kinase 2 (MK2), a member of the p38 signaling pathway, can also directly phosphorylate the S90 site of Beclin-1, which is essential for tumor suppression of Beclin-1 protein and can upregulate autophagy levels, maintain cellular homeostasis, and prevent tumorigenesis." (PMID 36104717, 2022). "mRNA levels of Beclin 1 were compared in 50 tissue pairs of normal tumor adjacent and corresponding tumor tissue and the results showed that Beclin 1 mRNA levels were significantly higher in the tumor tissues than in the normal tumor adjacent tissues (P < 0.05)." (PMID 36401689, 2022). "Interestingly, TRIM22 stimulates autophagy by promoting BECLIN 1 expression and has also been shown to play a role in driving tumor growth and progression." (PMID 35743294, 2022). "BECN1, an essential autophagy gene, was reported to play a pivotal role in tumor biology." (PMID 35012553, 2022). "At the same time, the protein kinase R-like ER kinase (PERK)/CHOP signaling pathway can motivate cell apoptosis; phosphorylated eukaryotic initiation factor 2α (p-eIF2α) can weaken tumor invasion; the deletion of Beclin-1 can result in the initiation of a tumor." (PMID 35327508, 2022).
tumor (continued). "Moreover, mutational activation of EGFR and ligand stimulation of wild-type EGFR has been reported to result in Beclin 1 tyrosine phosphorylation, which leads to autophagy suppression, tumor growth, and tumor dedifferentiation in NSCLC xenografts." (PMID 37192859, 2022). "Immunohistochemical staining with validated anti-ULK1 R170me2s or anti-ULK1 pT180 antibody revealed that ULK1 R170K mutation abolished ULK1 R170me2s, and reduced the phosphorylation of ULK1 T180, Atg13 S355, and Beclin 1 S15 in the tumor samples derived from the mice in normoxia condition." (PMID 35246531, 2022). "In contrast, Beclin-1 can promote tumorigenesis in a context dependent manner, as its complete knockout in triple negative breast cancer cells leads to cell cycle arrest, resulting in impaired tumor growth." (PMID 35883626, 2022). "Enhanced levels of autophagy may be related to a tumor-mediated upregulation of cardiac beclin-1 expression and cardiac inflammation (MyD88), which lead to increased cardiac atrophy (FOXO1 signaling)." (PMID 36531941, 2022). "Moreover, BECN1 is not only concerned in the autophagosomes formation, but also has an essential role in tumor formation by controlling autophagic activity." (PMID 36009242, 2022). "Notably, expression of ULK1 R170K mutation attenuated low-oxygen-induced phosphorylation of ULK1 T180, Atg13 S355 and Beclin 1 S15, and accordingly further curbed tumor growth with repressed cell proliferation and increased cell death." (PMID 35246531, 2022). "EGFR may play anti-autophagic role to affect tumor progression and chemoresistance by mediating Beclin 1 phosphorylation." (PMID 35739532, 2022). "Importantly, the knockdown of RB1 remarkably rescued the tumor growth inhibited by the BECN1 depletion." (PMID 36230664, 2022). "Thus, SOX2-β-catenin/Beclin-1/autophagy pathway is involved in tumor progression and chemotherapy resistance." (PMID 36160153, 2022). "Furthermore, ablation of BECN1 inhibited xenograft tumor growth, which was reversed by simultaneous silencing of RB." (PMID 36230664, 2022). "Therefore, Beclin 1 is the first tumor suppressor to be described as being under the control of Lys11-linked polyubiquitination." (PMID 36293239, 2022). "Based on these findings, it can be inferred that that Beclin-1 can block G2/M phase to delay cell cycle progression and induce autophagy and Beclin 1 may be a tumor suppressor factor." (PMID 36147481, 2022). "In addition, in the xenograft tumor mouse model, BECN1 ablation leads to robust inhibition of tumor growth, attributable to both upregulated RB expression and reduced autophagy." (PMID 36230664, 2022). "Finally, the strong expression of miR-216a in xenograft tumor models led to a reduction of the Beclin-1 expression and autophagy process with a consequent increase in cell sensitivity to irradiation treatment." (PMID 36558998, 2022). "Therefore, Beclin-1-mediated autophagy cell death is an important tumor suppressor mechanism, and Beclin-1 can be studied as a potential target for anticancer therapy." (PMID 36104717, 2022). "In particular, Beclin-1 may regulate tumor growth and progression through the control of endolysosomal trafficking of cell surface growth receptor function." (PMID 35309939, 2022). "The first mouse model with deletion of autophagy gene was established to study the role of autophagy in tumorigenesis, and the results indicated that the deletion of BECN1 (gene symbol of Beclin1) increased the rate of spontaneous tumor formation compared with BECN1 wild-type." (PMID 35211417, 2022). "In addition, circ_0020850 and BECN1 expression levels were decreased while miR-326 expression level was increased in xenograft tumor tissues of sh-circ_0020850 group." (PMID 35012553, 2022). "The tumor-suppressive role of autophagy has been established by the finding that several human cancers harbor allelic deletions in pro-autophagy genes, such as Beclin-1, PTEN, AMPK, LKB1, and TSC1/2." (PMID 35745567, 2022).
tumor (continued). "Besides, the treatment of bupivacaine promoted the expression ratio of light chain 3B-II (LC3B-II)/LC3B-I and the expression of Beclin-1 in the tumor tissues." (PMID 33777755, 2021). "Interestingly, accumulating evidence indicates that BECN1 phosphorylation is directly involved in autophagy and tumor progression, including proliferation, metastasis, and tumor chemoresistance." (PMID 34131122, 2021). "In agreement, increased Beclin1 activity (Becn1 knock-in mice expressing a mutated form of Beclin1 with decreased interaction to its inhibitor Bcl-2 or use of an autophagy-inducing peptide, Tat-Beclin1) prevented HER2-positive tumor xenograft progression." (PMID 34207792, 2021). "Beclin-1, Atg4, Atg5, and Atg7 have indicated a tumor-suppressive function." (PMID 34122670, 2021). "Hence, it is postulated that the high basal autophagy noted in these tumor samples indicated by increased Beclin-1 expression promotes tumor progression as well as treatment resistance." (PMID 34490076, 2021). "Moreover, BO downregulated the expressions of beclin-1, as well as several mRNA levels of autophagy-related genes (Beclin1, Atg5 and Lc3), suggesting that the inhibition on autophagy plays a critical role in tumor suppression by BO." (PMID 34658867, 2021). "Furthermore, these intracellular components can be recycled and used for tumour metabolic demands; however, suppressing autophagy through the partial deletion of the Beclin-1 gene leads to increased cell death." (PMID 34445354, 2021). "In addition, BECN1 heterozygous deletion leads to increased malignancies in mice, with decreased tumor growth when BECN1 expression is restored." (PMID 34944772, 2021). "One of the examples is that the genetic deletion of BECN1 enhances spontaneous tumour formation." (PMID 33605033, 2021). "Interestingly, the therapeutic benefit of paclitaxel was increased in a Becn1-targeted BT-474 xenograft mice model based on cleaved caspase-3 positive cells and inhibition of tumor growth." (PMID 33718194, 2021). "In addition, inhibition of autophagy overcame HSPA5-mediated resistance, and the simultaneous knockdown of HSPA5 and Beclin-1 restored sensitivity in resistant tumor cells." (PMID 33902430, 2021). "Furthermore, the in silico CPTAC sample analysis showed low Beclin 1 protein expression in the tumor parts compared to the non-tumor parts." (PMID 34737955, 2021). "For instance, Becn1 has been reported to be a tumour-suppressor gene." (PMID 34511147, 2021). "Similarly, CRAds, which use the survivin promoter, enhance autophagy in glioma infected cells and favor the elimination of tumor cells via a beclin-1 dependent mechanism." (PMID 34745965, 2021). "This indicates that BRCA1 deletions are the main drivers of tumorigenesis, and so BECN1’s role as a tumor supressor remains unclear." (PMID 33459128, 2021). "Moreover, the tumor suppressor function of Beclin-1 is exerted through binding and activating Vps34 which lead to induce autophagy." (PMID 34660642, 2021). "However, the effect of Beclin-1 expression levels on tumor cell invasiveness only appeared in combination with high Bcl-2 expression (there were no observed differences in other groups)." (PMID 34257544, 2021). "These latter findings are in direct alignment with the tumor suppressor role of BECN1." (PMID 34944772, 2021). "Herein, BECN1 deletion would avoid the membrane localization of E-cadherin, a protein with tumor suppressor properties, favoring the transcription of genes involved in tumor progression." (PMID 34830777, 2021). "The inhibition of hsa-miR-30a may retard tumor progression by decreasing Beclin-1 and ATG5 expression and inhibiting autophagy, thereby sensitizing the tumor cells to the drug therapy." (PMID 34203465, 2021). "Likewise, BECN1 inhibition increased functional NK cell tumor infiltration in a melanoma mouse model." (PMID 33335860, 2020).